IGFBP5 (insulin like growth factor binding protein 5)
Diseases named in the same sentence as IGFBP5 in open-access papers (continued):
Sharing a sentence is not in itself a finding about the gene and the disease.
prostate carcinoma (13 papers, 2009 to 2025). A carcinoma that arises from epithelial cells of the prostate gland. "Androgen replacement via testosterone stimulation of castrated mice secondary to prostate cancer xenografts caused an increase in IGFBP5, indicating IGFBP5 may be regulated by the androgen receptor (AR) in some cases." (PMID 36465383, 2022). "In prostate cancer, where androgen deprivation causes prostate carcinoma and stromal cells to upregulate the IGFBP5 level, overexpression of IGFBP5 enhances the anti-apoptotic and mitogenic activity of recombinant IGF1 protein, thereby helping to overcome castration-induced tumor regression." (PMID 36093095, 2022). "IGFBP5 expression in prostate cancer tissue and prostate carcinoma is significantly lower than normal tissue, while overexpression of IGFBP5 enhances radiosensitivity." (PMID 36465383, 2022). "Clinical studies in prostate cancer show that increased expression of IGFBP5 improves the efficacy of radiotherapy for localized prostate cancer, and in vitro IGFBP5 overexpression induced G2/M phase cell cycle arrest via PI3K/AKT signaling." (PMID 36465383, 2022). "In a mouse model of prostate cancer, upregulation of IGFBP-5 following androgen withdrawal by castration was found to potentiate IGF signaling in vivo, which led to faster progression to androgen dependence." (PMID 32194505, 2020). "In prostate cancer cells, down regulation of IGFBP-5 inhibited IGF-dependent growth in vitro and in vivo and castration induced upregulation of IGFBP-5 in mice accelerated the development of androgen independence." (PMID 25866791, 2015). "Genes encoding secreted proteins ADAMTS1, IGFBP5 and WNT5A were significantly down-regulated in NCCIT cells co-cultured with CD90+ prostate cancer-associated fibroblasts compared to induction by normal prostate stromal cells." (PMID 24260246, 2013). "IGFBP-5 overexpression in prostate cancer cells after castration is an adaptive cell survival mechanism that helps potentiate the anti-apoptotic and mitogenic effects of IGF-I, thereby accelerating progression to androgen independence." (PMID 29147215, 2010). "By increasing the efficacy of radiotherapy as a monotherapy, IGFBP5 treatment could present a viable option for prostate cancer patients to subvert the need for ADT." (PMID 36465383, 2022). "However, stress-induced increase in several antiapoptotic genes, such as bcl-2, clusterin, insulin-like growth factor binding protein-2 (IGFBP-2), IGFBP-5 and heat-shock protein 27, have been shown to have important functions in the AI progression of prostate cancer after castration." (PMID 19844233, 2009). "It was reported that castration of male mice induces local IGFBP-5 expression in prostate tissue and the elevated IGFBP5 increases IGF action and promotes prostate cancer progression." (PMID 32194505, 2020). "Previous studies report that IGFBP5 influences pancreatic cancer cell growth and survival via the MAPK or PI3K pathway, and enhances prostate cancer growth through activation of the PI3K pathway." (PMID 26010068, 2015). "Furthermore, analysis of the TCGA PRAD cohort revealed a significant correlation between expression of FUT8 and genes for IGFBP5, IL1B and PTGES3 in clinical prostate cancer tissue." (PMID 40387385, 2025). "Evaluation of the altered pathways showed that AR, IGF1, IGFBP5 and ETV1 were markedly decreased in the AfA derived cell line compared with CaA cells, and there was a reciprocal regulatory relationship of miR-24/target expression in prostate cancer patients." (PMID 28157714, 2017).
idiopathic pulmonary fibrosis (12 papers, 2011 to 2025). Idiopathic pulmonary fibrosis (IPF) is a nonneoplastic pulmonary disease that is characterized by the formation of scar tissue within the lungs in the absence of any known cause. "We previously reported that IGFBP-5 levels were increased in two fibrotic disorders, systemic sclerosis (SSc) and idiopathic pulmonary fibrosis (IPF)." (PMID 26103640, 2015). "We also reported that IGFBP-5 mRNA and protein levels are increased in vivo in lung tissues of patients with idiopathic pulmonary fibrosis (IPF) and in vitro in primary fibroblasts cultured lung tissues of patients with SSc and those with IPF." (PMID 24551065, 2014). "Beyond its role in development, IGFBP5 has been investigated in pathologies such as idiopathic pulmonary fibrosis (IPF), liver disease, obesity, and the negative impacts of aging." (PMID 36465383, 2022).
ovarian carcinoma (11 papers, 2010 to 2023). A malignant neoplasm originating from the surface ovarian epithelium. "In GSE26712, we divided ovarian cancer patients into two risk groups based on the expression of IGFBP5." (PMID 37199034, 2023). "Furthermore, in GSE26712, we divided ovarian cancer patients into two risk groups with a cut‐off of 6.508 based on the level of IGFBP5." (PMID 37199034, 2023). "We have explored the expression of IGFBP5 protein in clinical samples and found that IGFBP5 was downregulated in ovarian cancer." (PMID 37199034, 2023). "Compared with IGFBP3, the studies on the relationship between IGFBP5 and ovarian cancer are limited." (PMID 37199034, 2023). "Validation results in ovarian cancer suggested that IGFBP5 can be a candidate and promising prognostic marker." (PMID 37199034, 2023). "It has been reported that IGFBP5 by acting as an anti‐angiogenic factor, prevents tumor growth and inhibits tumor vascularity in human ovarian cancer." (PMID 35866351, 2023). "An assessment of IGFBP5 revealed that the greatest rate of CNVs is found in ovarian cancer, with over 25% of patients possessing either an increase or decrease in copy number of the IGFBP5 gene." (PMID 36465383, 2022). "Endometrioid ovarian cancer cells expressing a truncated peptide for each domain of IGFBP5 (C, L and N) had varying effects on tumor growth in a subcutaneous injection model." (PMID 36465383, 2022). "In ovarian cancer, the ratio between miR-661 and the circular lnc-RNA circPIP5K1A plays a role in regulating IGFBP5 translation." (PMID 36093095, 2022). "In ovarian cancer, as previously discussed, increased IGFBP5 was positively correlated with decreased overall survival, suggesting it is important for cancer progression." (PMID 36465383, 2022). "Of note, a repressive effect of estrogen on IGFBP5 was also found with the estrogen-sensitive PE04 ovarian cancer cell line." (PMID 36093095, 2022). "Expression of C-terminal region of IGFBP-5 significantly decreased tumor growth in an ovarian cancer xenograft." (PMID 28008951, 2016). "In this study, we aimed to evaluate the functional significance of IGFBP-5 as a tumor suppressor in ovarian cancer using in vitro and in vivo systems." (PMID 28008951, 2016). "We analyzed global gene expression in ovarian cancer tissues obtained from 30 ovarian cancer patients using cDNA microarray analysis and found that IGFBP5 expression was significantly downregulated in ovarian cancers compared with normal ovarian tissues." (PMID 28008951, 2016). "A synthetic peptide derived from the C-terminus of IGFBP-5 inhibited angiogenesis and tumor growth in an in vitro system and in ovarian cancer xenograft animal systems." (PMID 28008951, 2016). "We examined the IGFBP5 expression level in several ovarian cancer cell lines using reverse transcription PCR (RT-PCR) and found that it was downregulated in cancer cell lines relative to levels in the IOSE normal ovarian cell line." (PMID 28008951, 2016). "Ectopic expression of IGFBP-5 induced cell death in ovarian cancer cells, demonstrating its function as a tumor suppressor." (PMID 28008951, 2016). "IGFBP-5 expression prevented tumor growth and tumor vascularity, indicating a tumor suppressor role in ovarian cancer." (PMID 20069126, 2010). "Our results could provide underlying targets for the design of laboratory experiments to elucidate the mechanism of IGFBPs in cancers and identify IGFBP5 as a prognostic factor in ovarian cancers." (PMID 37199034, 2023). "Exogenous administration of IGFBP5 protein showed that IGFBP5 could promote the procession of EMT in ovarian cancer cells." (PMID 37199034, 2023). "Our data suggested that IGFBP5 can serve as an independent prognostic factor in ovarian cancer." (PMID 37199034, 2023). "CircPIP5K1A promotes development of ovarian cancer by regulating miR-661/IGFBP5 axis." (PMID 34774083, 2021).
ovarian carcinoma (continued). "Our results suggest that a peptide derived from the C-terminus of IGFBP-5 may serve as a novel angiogenesis inhibitor for the treatment of ovarian cancer." (PMID 28008951, 2016). "In this study, we found that IGFBP5 was markedly downregulated in ovarian cancer tissue." (PMID 28008951, 2016). "IGFBP-5 function in angiogenesis was also studied in a xenograft model of ovarian cancer." (PMID 20069126, 2010). "Additionally, IGFBP5 has been proved that promotes the invasion and migration of ovarian cancer." (PMID 37199034, 2023). "Additionally, IGFBP5 was proved which promotes the invasion and migration of ovarian cancer cells." (PMID 37199034, 2023). "Estrogen down-regulates IGFBP3 and IGFBP5 and up-regulates IGFBP4 in ERα-positive ovarian carcinoma cells." (PMID 32580290, 2020). "The letrozole response is similarly associated with these modified levels of expression in ERα-positive ovarian carcinomas, and this has been confirmed for both IGFBP3 and IGFBP5 in subsequent trials." (PMID 32580290, 2020). "Although IGFBP5 has not been studied in the context of drug resistance in ovarian cancer, a bioinformatic analysis of cisplatin resistant ovarian cancer cell lines identified IGFBP5 as significantly downregulated when compared to the parental cell line." (PMID 36465383, 2022). "Thus, it is not surprising that calcitriol treatment induces IGFBP5 expression in ovarian cancer cells." (PMID 29581858, 2018). "Moreover, using immunohistochemical staining for IGFBP-5, we detected expression in the nuclei of cells in normal ovarian epithelium, but not in ovarian cancer tissue." (PMID 28008951, 2016).
pancreatic cancer (10 papers, 2015 to 2024). "Overexpression of TYMS and IGFBP5 has been reported to be associated with shorter survival time and poorer disease outcomes in human pancreatic cancer and urothelial carcinoma, respectively." (PMID 36139323, 2022). "IGFBP-5 expression is an important mediator of pancreatic cancer cell growth." (PMID 32127912, 2020). "Interestingly, both IGFBP3 (two probes, more than eight folds) and IGFBP5 (three probes, more than 3 folds) are dramatically increased in both pancreatic tumor datasets, whereas, IGFBP2 is significantly decreased in both datasets." (PMID 26975989, 2016). "Observed significant association between pancreatic cancer risk and polymorphisms in IGF1, IGF1R & IGFBP1 but SNPs in IGFBP5 were not significant." (PMID 36465383, 2022). "CLUSTER1 also included up-regulated genes with unknown importance in pancreatic cancer, such as MATN3, SERPINA1, and IGFBP5." (PMID 33194391, 2020). "Pancreatic cancer cells transfected with miR-375 showed the down-regulation of insulin-like growth factor-binding protein-5 (IGFBP5) and caveolin-1 (CAV1), and BITC possibly targeted the up-regulation of IGFBP5 and CAV-1 through suppressing the expression of miR-221 and miR-375." (PMID 36765652, 2023). "Excess IGFBP5 has been shown to regulate myotube differentiation probably via modulation of IGF-2 signaling, however, whether IGFBP-3, which predominantly binds to IGF-1 and exhibits the greatest induction in pancreatic tumors, affects myogenesis is largely unknown." (PMID 26975989, 2016).
breast tumors (9 papers, 2005 to 2025). "Since IGFBP5 is a physiological regulator of epithelial cell survival in the mammary gland, it was proposed that a deregulation of IGFBP5 expression induced by variants located upstream of DIRC3 could lead to the development of a breast tumour." (PMID 33747362, 2021). "We tried to identify differentially expressed genes (DEGs) between breast tumor tissues with IGFBP5 overexpression and their adjacent normal tissues." (PMID 26569312, 2015). "Note, insulin like growth factor 1 (Igf1) and insulin like growth factor binding protein 5 (Igfbp5) were decreased or unchanged in confounders but increased in breast tumor-bearing mice." (PMID 21589862, 2011). "There have been very few observations of nuclear localisation of IGFBPs in vivo, with cytoplasmic IGFBP-5 expression in breast tumours and, similarly, cytoplasmic IGFBP-3 in normal colonic crypts[B6,9]." (PMID 15642160, 2005). "IGFBP5 was found overexpressed in breast tumors compared to normal breast tissues." (PMID 37620794, 2023). "In the disease association analysis (neoplasms, cancer or viral infections, breast neoplasms, neuroblastoma), the LMO3, MYB and BIRC3 oncogenes were also significantly upregulated whereas the WISP2, IGFBP5 and RASSF2 tumour suppressor genes were significantly downregulated in FFs compared to NFs." (PMID 28717200, 2017).
colon cancer (9 papers, 2010 to 2026). "Functional assays revealed that ERβ knockdown inhibited colon cancer cell proliferation and migration, accompanied by a marked reduction in IGFBP-5 expression." (PMID 42047268, 2026). "In colon cancer, IGFBP5 is assumed to be upstream of WNT signaling and promotes cell growth via activation of the WNT pathway." (PMID 37566084, 2023). "Anticancer activity of tetrandrine in colon cancer may be mediated by downregulation of IGFBP5 expression that inactivates the canonical Wnt pathway." (PMID 36465383, 2022). "Also, the interaction between 25(OH)D and IGFBP2/IGFBP5 was statistically significant for colon cancer." (PMID 31434255, 2019). "Using the same hypothesis-driven supervised approach focused on IGF pathway member expression, Pavlicek and al., also identified IGFBP5 as a biomarker of colon cancer cells sensitivity to another IGF1R tyrosine kinase inhibitor, Figitumumab." (PMID 28882129, 2017). "Thus, MASP3-mediated cleavage of IGFBP-5 might hinder its ability to bind IGF-I suggesting that this linkage between MASP3 and IGFs could constitute an important mechanism for colon cancer progression." (PMID 24243807, 2013).
gastric cancer (9 papers, 2019 to 2025). A primary or metastatic malignant neoplasm involving the stomach. "ROC analyses revealed that IGF-1, IGFBP-4, and IGFBP-5 have good discriminatory properties in the diagnosis of gastric cancer, while PAPP-A offers low diagnostic value." (PMID 41303367, 2025). "Therefore, the low IGFBP-5 levels in our study might indicate a loss of this inhibitory effect in gastric cancer." (PMID 41303367, 2025). "ROC analysis further showed that IGFBP-5 can discriminate gastric cancer patients from healthy individuals with an AUC of 0.768, supporting its potential as a clinically related biomarker." (PMID 41303367, 2025). "Bioinformatics analysis also demonstrated significantly lower IGFBP-5 expression in gastric cancer tissues." (PMID 41303367, 2025). "In breast and stomach cancers, the increased expression of IGF1R, GPC3, and IGFBP5 genes is associated with tumor progression and metastasis." (PMID 30944407, 2019). "In conclusion, this study suggests that IGF pathway components, particularly IGF-1, IGFBP-4, and IGFBP-5, might be promising biomarker candidates for gastric cancer." (PMID 41303367, 2025). "In another study using 11 gastric cancer cell lines, IGFBP-5 was expressed in 50% of the cells." (PMID 41303367, 2025). "On the other hand, IGFBP5 can suppress the gastric cancer cell growth." (PMID 32127912, 2020). "Moreover, ROC analysis showed that IGF-1, IGFBP-4, and IGFBP-5 could effectively distinguish gastric cancer from healthy controls with high sensitivity and specificity." (PMID 41303367, 2025). "It has also been reported that IGFBP-5 may play a tumor-suppressing role in gastric cancer." (PMID 41303367, 2025). "In the gastric cancer serum sample, IGF-1 and IGFBP-5 were the most accurate biomarkers in differentiating between gastric cancer patients and healthy individuals." (PMID 41303367, 2025). "In this study, serum levels of IGF signaling pathway-related proteins known as IGF-1, IGFBP-4, IGFBP-5, and PAPP-A were compared between gastric cancer patients and healthy controls." (PMID 41303367, 2025). "This study investigated the biomarker potential of IGF-1, IGFBP-4, IGFBP-5, and PAPP-A in gastric cancer." (PMID 41303367, 2025). "In this study, IGF-1, IGFBP-4, IGFBP-5, and PAPP-A levels were examined in serum samples obtained from gastric cancer patients and healthy individuals." (PMID 41303367, 2025). "Overall, these results demonstrate that the IGF signaling pathway plays a critical role in the pathogenesis of gastric cancer and that IGF-1, IGFBP-4, and IGFBP-5, in particular, may serve as potential biomarkers for clinical applications." (PMID 41303367, 2025). "A study of 11 gastric cancer cell lines demonstrated that IGFBP1 expression levels were extremely low in all cell lines, whereas IGFBP2 and IGFBP4 were expressed in 10 and 9 cell lines, respectively, and IGFBP3, IGFBP5, and IGFBP6 were expressed in half of all cell lines." (PMID 34745945, 2021).